ICAM1 (intercellular adhesion molecule 1)
Diseases named in the same sentence as ICAM1 in open-access papers (continued):
Sharing a sentence is not in itself a finding about the gene and the disease.
tumor (continued). "Additionally, cancer cells may overexpress several surface receptors, including CD46, ICAM-1 (CD54), DAF (CD55), CD155 and integrins, which enable OVs to enter tumor cells in the TME." (PMID 32411132, 2020). "IRI-induced inflammatory cytokines, including TNF-α or IL-1, may promote the development of metastases in several types of cancer cells via the expression of adhesion molecules (e.g., e-selectin, ICAM-1, and vascular cell adhesion molecule 1 (VCAM-1)), which act as mediators for tumour growth." (PMID 32806712, 2020). "ICAM-1 inhibits the efferocytosis of apoptotic tumor cells through the suppression of the PI3K/Akt signaling pathway, and the downregulation of efferocytosis leads to the decrease of M2 macrophage polarization, consequently inhibiting tumor progression and tumor metastasis." (PMID 32370748, 2020). "Finally, CBD did not induce LAK cell-mediated lysis and upregulation of ICAM-1 of non-tumor bronchial epithelial cells, suggesting this effect is specific to cancer cells." (PMID 33143283, 2020). "Notably, normal pancreatic tissues adjacent to PC tumors were not targeted by ICAM1 antibody, further confirming its PC tumor‐specificity." (PMID 33344137, 2020). "Thus, we investigated whether FUS-induced inflammation led to differences in expression of cell adhesion molecules E-selectin, P-Selectin, ICAM-1, and VCAM-1 on intracranial B16F1cOVA tumor CD31+ endothelial cells 6 hours post FUS+MBs BTB/BBB opening." (PMID 32754281, 2020). "Indeed, sunitinib treatment resulted in upregulated expression of ICAM-1 and VCAM-1 adhesion molecules on endothelial cells of tumor bearing mice, with several studies reporting that infiltration of TILs is markedly increased in animal tumor models and in humans after VEGF inhibition." (PMID 33121034, 2020). "Glycans on endothelial adhesion molecules including ICAM-1, VCAM-1, and PECAM, and glycan-binding proteins (lectins) expressed on the surfaces of endothelial, immune, and cancer cells, alter the adhesive properties of endothelial cells and facilitate (or disfavor) immune and tumor cell infiltration." (PMID 31195728, 2019). "Moreover, tumor cell metastasis related gene products, such as VEGF, MMP-9, and ICAM-1, could be mitigated by FCN." (PMID 31466313, 2019). "Icam-1 facilitates the binding of leukocytes to vascular endothelium after extravasation, and CCL-5 is highly expressed by T-cells and can recruit leukocytes to the tumor microenvironment, indicating a pro-inflammatory function, which is increased in the absence of Pecam-1." (PMID 31344919, 2019). "The observation that ICAM-1 did not compensate for lack of CD11b-mediated adhesion in EO-tumor cell conjugates upon CD11b/CD18 blockade further supports the major role played by CD11b/CD18 in mediating tumor cell adhesion and subsequent cytotoxicity in IL-33 EO." (PMID 31717819, 2019). "The adhesion ligand Mac-1 on DCs can bind to the adhesion molecule intercellular adhesion molecule-1 (ICAM-1), which is upregulated on endothelial cells of collecting lymphatic vessels in response to inflammation, including inflammation generated by the tumor microenvironment." (PMID 29527513, 2018). "While tumors treated with T-cells pre-cultured on uncoated substrates continuously grew in size over time, the tumors treated with T-cells cultured on CCL21 + ICAM1 substrates displayed almost no increase in tumor size, throughout the follow-up period (14 days)." (PMID 29942308, 2018). "Notably, the remaining triple negative tumors did not stain positively for ICAM1 in tumor cells, but all showed positive staining for ICAM1 expression in infiltrating immune cells." (PMID 30082828, 2018). "One mechanism in which tumor vasculature can prevent immune cell extravasation into the TME is through downregulation of adhesion molecules on endothelial cells such as E-selectin, intercellular adhesion molecule (ICAM)-1/2, and vascular cell adhesion molecule (VCAM)-1." (PMID 30558196, 2018).
tumor (continued). "The blocking of the integrins tetraspondin, ICAM-1 and LFA-1 with specific antibodies partially inhibits the interaction of dendritic cell-derived EVs with recipient dendritic cells, and heparan sulphate proteoglycans expressed by tumor-EVs are recognized by tumor cells." (PMID 30326618, 2018). "Furthermore, intravenous injection of CVA21 expressing ICAM-1 and DAF in combination with intraperitoneal injection of doxorubicin hydrochloride provided significantly enhanced tumor regression in comparison to either virus or drug alone in mice with implanted MDA-MB-231 tumors." (PMID 29883422, 2018). "Most importantly, tumor suppression by T-cells pre-cultured on CCL21 + ICAM1 persisted throughout the 14-day experiment, with almost no increase in tumor size over time, compared to the constantly growing tumors treated with T-cells pre-cultured on uncoated substrates." (PMID 29942308, 2018). "In addition to the central nervous system, highly glycosylated IgSF-CAM members also play critical roles in other systems affected in CDG patients, such as the developing eyes and immune system with ICAM1, or in other diseases like cancer, where L1CAM plays a critical role in tumor metastasis." (PMID 30311906, 2018). "RT has also been shown to stimulate tumor cell release of chemokines CXCL16 and CXCL10, to increase the expression of adhesion molecules E-selectin and ICAM-1 in endothelial cells and to upregulate major histocompatibility complex (MHC1), Fas, ICAM-1, and NKG2D ligands." (PMID 28344743, 2017). "The blocking of neither ICAM-1 nor VCAM-1 had any effect on the PT-induced tumor cell adhesion." (PMID 29100413, 2017). "We show that ICAM-1 is upregulated in OS CSC exposed to non-tumor component, but could not confirm previous data showing its dependency on IL-6." (PMID 27851822, 2016). "Importantly, downregulation of WISP1 in vivo also induced decrease in expression of ICAM-1, VCAM-1, VEGFC, MMP-2, MMP-9 and increase in E-cadherin, suggesting that WISP1 downregulation not only inhibited tumor growth but also suppressed tumor metastasis in vivo." (PMID 27409174, 2016). "The tumor tissues were implanted into nude mice and subjected to pathological examination, immunohistochemical staining, and real-time PCR for cytokeratin 8/18 (CK8/18), E-cadherin, vascular cell adhesion molecule-1 (VCAM-1) and intercellular adhesion molecule-1 (ICAM-1)." (PMID 26847082, 2016). "Finally, celecoxib elicited no significant increase of LAK cell-mediated lysis of non-tumor bronchial epithelial cells, BEAS-2B, associated with a far less ICAM-1 induction as compared to cancer cells." (PMID 26513172, 2015). "For example, the intercellular cell-adhesion molecule-1 (ICAM-1), a transmembrane molecule and a distinguished member of the immunoglobulin superfamily of proteins, was involved in tumor invasion and EMT, and was also correlated with tumor differentiation grade and survival of NSCLC patient." (PMID 25477004, 2014). "In addition, we found that ICAM-1 acts as a crucial transducer of cell signaling that regulates cell migration, whereas IL-6 acts as a critical mediator of metastasis activity of OSCC cells in the tumor microenvironment." (PMID 24398980, 2014). "In addition, we also provided the evidence that ICAM-1 acts as a crucial transducer of cell signaling, regulating cell migration, and WISP-1 acts as a critical mediator of the metastasis activity of OSCC cells in the tumor microenvironment." (PMID 24205072, 2013). "In contrast, high concentrations of soluble ICAM-1 (sICAM-1) were detected in malignant pleural fluid samples and A549 supernatants compared with plasma from NSCLC patients and healthy controls, implying that the level of sICAM-1 is high in the tumour microenvironment." (PMID 23565296, 2013).
tumor (continued). "In addition, in tumor tissues a higher expression of adhesion molecules (ICAM-1, VCAM-1, or E-selectin) in endothelial cells and a significantly higher number of infiltrated leucocytes is observed within the tumor treated with 16K hPRL compared with the untreated ones." (PMID 22087289, 2011). "Contradictorily, radiation-induced translocation of other intracellular proteins such as P-Selectin and intercellular adhesion molecule-1 (ICAM-1) are reportedly associated with inflammatory response to ionizing radiation and thus not specific to tumor response to the radiation treatment." (PMID 20711449, 2010). "While ICAM1 and VCAM1 are also expressed outside the vasculature (e.g., by cancer-associated fibroblasts and myeloid cells), the vascular selectins are exclusively expressed by endothelial cells and (for P-selectin) platelets, but not on tumor cells or other stromal populations." (PMID 40796746, 2025). "Notably, despite the increased ICAM-1 expression observed in tissue sections, its overall expression levels remained the same across WT, PAK1KO, and PAK4KO cancer cell lines, suggesting that the upregulation primarily originates from the tumour stromal cells within the TME." (PMID 40943273, 2025). "Tumour cells also express ICAM-1 or VCAM-1, which may not stimulate anti-tumour immunity." (PMID 40943273, 2025). "Inspired by the RNA‐seq results that DAC could upregulate ICAM1 expression and reprogram the tumor microenvironment (increasing infiltrating immune cells, upregulating chemokines and downregulating collagen formation genes), we speculated that DAC may improve tumor penetration of I1‐DXd." (PMID 38874532, 2024). "Therefore, examination of tumor infiltration markers such as LFA-1 and ICAM-1 could be important." (PMID 38380966, 2024). "However, ICAM1-ΔTM-ΔC-GPI was not as efficient as full-length ICAM1 in rescuing tumor killing." (PMID 37732732, 2023). "Likewise, as demonstrated here, not only drugs targeting the VEGF axis can overcome tumor endothelial cell anergy, also drugs targeting epithelial growth factor receptor (EGFR, erlotinib) and platelet derived growth factor receptor (PDGFR, crenolanib) can normalize ICAM-1 expression." (PMID 36459240, 2023). "Additionally, it has been reported that ICAM-1 on TAMs could bind CD18 on Myeloma cells to regulate drug resistance, and this contact-dependent interaction tended to expand M2 infiltration and release cells from tumor cell aggregates." (PMID 36497444, 2022). "Finally, we inhibited expression of E-selectin, ICAM-1 and VCAM-1 using a siRNA mixture of siE-selectin, siICAM-1 and siVCAM-1, which blocked upregulation of expression of these adhesion molecules, as well as the increase in tumor cell adhesion induced by HECTD3 overexpression in HUVECs." (PMID 35918322, 2022). "In immune analysis, ICAM1, IL1B, IL-6, MMP1, MMP3, MMP9, and SERPINE1 all showed positive correlations with most immune cells, implying that CC and MF may exert an antitumor activity by interacting with these genes and immune cells, and thus control tumor development." (PMID 35783510, 2022). "Notably, antibiotic-induced dysbiosis could not augment the tumor-promoting potential of ICAM-1 deficiency, suggesting that ICAM-1 mediated dysbiosis-induced tumor development." (PMID 36726985, 2022). "We examined surface expression of an intercellular adhesion molecule 1 (ICAM-1), a key adhesion molecule for both T cell and NK cell synapses, and found that their expression levels and surface densities were not significantly influenced by the adhesion status of tumor cells." (PMID 36389663, 2022). "Interestingly, it has been reported that ET-1 released by ovarian cancer cells may affect the recruitment of TIL to the tumor via ETBR, reducing the expression of the endothelial intercellular adhesion molecule 1 (ICAM1), therefore interfering with the TIL homing to the tumor." (PMID 33422090, 2021).
tumor (continued). "In addition, tumor vascular ECs also downregulates the level of adhesion molecules on cell surface, which limits the trafficking of immune effector cells into tumors, such as vascular cell adhesion molecule-1 (VCAM-1) and intercellular adhesion molecule-1 (ICAM-1)." (PMID 34930293, 2021). "Several hypotheses have been made in order to unveil the mechanisms used by tumor cells to remain within the vessel lumina; for instance, lower levels of molecules involved in trans-vascular migration, namely CD29 (integrin 1ß) and CD54 (ICAM1) has been detected in IVLBCL cells." (PMID 33499258, 2021). "Interference in the ICAM-1 signal obtained by the ICAM-1 monoclonal antibody by mouse-specific expression of the ICAM-1 molecule in vivo (which may be altered by the presence of the xenograft tumour) has not been excluded." (PMID 32135474, 2020). "Thus, the potential of targeting ICAM-1 to alter cisplatin sensitivity in OAC needs further exploration, as it has direct effects on numerous cell types, including both cancer and endothelial cells, and is reliant on interactions with the tumour microenvironment." (PMID 30791601, 2019). "In addition, mainly anti-ICAM-1 and anti-VAP-1 and to a lesser extent anti-VCAM-1 mAbs inhibited HCC-derived T cell binding to tumor vascular endothelium in vitro suggesting that LFA-1/ICAM-1 and VAP-1 receptor/VAP-1 are crucial pathways mediating T cell recruitment into the tumor site in HCC." (PMID 31231358, 2019). "Due to cross-reactivity of our CAR T cells between human and mouse ICAM-1, the lack of on-target, off-tumor toxicity by micromolar affinity CAR T cells in mice with human tumor xenografts could be used to support specificity of our CAR T cells toward ICAM-1 high tumors in humans." (PMID 31337787, 2019). "Initially, we identified both monocytes (CD14+) and pDC as cell populations which expressed significantly more ICAM-1 than NK cells, CD4+ and CD8+ T cells, therefore, we hypothesized that these two cell types may act as key regulators of CVA21-mediated anti-tumor immunity." (PMID 31262361, 2019). "In the case of BiTE®-induced bystander killing, FAS and ICAM-1 were both upregulated on the antigen-negative cells, which helped contribute to the bystander killing process that took place over a matter of hours after initial contact of the BiTE® with the antigen-positive tumor cells." (PMID 31544847, 2019). "No positive ICAM1 staining of the tumor cells could be detected within the LNs (data not shown)." (PMID 30082828, 2018). "However, tumor irradiation did not modulate ICAM-1 expression." (PMID 24480782, 2014). "Therefore, SCE-H may help inhibit tumor invasion or progression via MMP-9 and/or ICAM-1." (PMID 23024755, 2012). "Shedding of other adhesion proteins such as L-selectin, ICAM-1 or VCAM, on the other hand, might be expected to modulate binding of tumour cells to the vasculature wall and thus play a role in the intravasation [i.e., exiting of tumour cells from the vasculature into a distant organ]." (PMID 21906355, 2011). "Genetic ablation of ICAM-1 significantly attenuates RT-induced metabolic flares in irradiated tumors, primarily due to reduced 18F-FDG uptake by tumor-infiltrating T cells rather than myeloid cells." (PMID 41416923, 2025). "On days 8 and 12, we observed a reduction in tumor burden in CD4IL10-treated U937-WT, but not in the ICAM1-KO group; the reduction on day 12 was statistically significant." (PMID 38724673, 2024). "IFNγ and ICAM-1 dependent conjugation formation between hHER2-CAR-T cells and target tumor cells was further confirmed by incubating tumor cells with recombinant IFNγ with/without an anti-LFA-1 blocking antibody." (PMID 37388744, 2023). "Surprisingly, the responses were not correlated with an increase in viral signaling proteins (RIG-I, TLR7, and TLR8), viral entry proteins (ICAM-1 and DAF), or PD-L1, nor was an inflamed tumor microenvironment found." (PMID 37569757, 2023).
tumor (continued). "Tumor densities of CD68+ and CD163+ cells were not different in C2D1 biopsies; neither those of DC-LAMP+, IDO1+, ICAM1+ or CD31+ cells (data not shown)." (PMID 35794623, 2022). "Employing neutralizing antibodies against E-selectin, ICAM-1 and VCAM-1 revealed that anti-E-selectin was able to block tumor cell binding, while anti-ICAM-1 and anti-VCAM-1 failed to significantly block tumor cell binding." (PMID 33854965, 2021). "Next, to assess the non-specific cytotoxicity of anti-ICAM1 CAR-T cells, we established a mouse model with SKBR3-luc xenograft tumor." (PMID 33072116, 2020). "Although blockade of ICAM-1/LFA-1 interaction, using anti-ICAM-1 mAbs, did not alter the extent of tumor lysis, blocking NKG2D and DNAM-1 alone, or in combination, significantly lowered NK cytotoxicity up to 70% (left)." (PMID 31024520, 2019). "Unexpectedly, we found that despite significantly higher levels of basal and inducible surface ICAM-1 expression, EWS-FLI1 siRNA treated (low) cells do not demonstrate enhanced T-cell mediated tumor cell apoptosis." (PMID 31164960, 2019). "This adhesion required intercellular adhesion molecule 1 (ICAM-1) and augmented tumor immunotherapy in vivo without increasing systemic antitumor immune response." (PMID 30101129, 2018). "When comparing the genes from the Tumor versus Normal, TLS positive versus TLS negative and TLS positive versus Normal with the interaction partners of ICAM1, four genes were identified." (PMID 30082828, 2018). "The IHC and real-time PCR results revealed that ICAM-1, VCAM-1, and CK8/18, but not E-cadherin, were predominantly expressed at surgery and in the implanted tumor of primary and first generation." (PMID 26847082, 2016). "TNFα also helps to remodel tumor microvasculature lacking the factors needed for CTL attachment and extravasation: P and E-Selectins, ICAM-1, VACM-1." (PMID 25592450, 2015). "Even though the correlations were not significant, it is possible that HO-1, ICAM-1, and CXCL10 play roles in the tumor growth of CRC." (PMID 26087182, 2015). "Previous studies have shown that the expression of ICAM-1, a ligand for CD11b/CD18 (also referred to as Mac-1 and CR3), is frequently reduced or absent in NSCLC with tumour cell dissemination." (PMID 23565296, 2013). "In PAK1KO PC cells, the expression of ICAM-1 was not changed, while VCAM-1 was increased by about 150%, suggesting that the increased ICAM-1 and VCAM-1 in PAK1KO tumour tissues were predominantly induced in non-tumour stromal cells rather than tumour cells." (PMID 41228228, 2025). "Analysis of tumor samples from NSCLC patients has shown that low, but not high, levels of IFN-γ and high expression of ICAM1 in the tumor microenvironment are positively correlated with enrichment in CD133+ cells and the highest expression of stemness-related genes." (PMID 38139154, 2023). "However, ICAM1 levels, and [111In]In-anti-ICAM-1 uptake in tumours was no different after irradiation (uptake 9.2%ID/g versus 14.8%ID/g)." (PMID 32135474, 2020). "While tumor cells do not express leukocyte-specific β2 integrins, for example LFA-1, tumor cells that express ICAM-1 facilitate their adherence to leukocytes, particularly neutrophils, through β2 integrins, which in turn bind to the endothelium, thereby promoting metastasis." (PMID 31552050, 2019). "On the other hand, expression of ICAM1 by the tumor cells might lead to specific T cell recognition and enhancement of effector CTL adhesion that might not be in favor for the tumor cells." (PMID 30082828, 2018). "Adhesion molecules including ICAM-1, VCAM-1, and E-selectin may be absent or expressed at low levels on tumor vasculature, despite the inflammatory microenvironment of the tumor." (PMID 28066431, 2016). "We confirmed that three of these candidates (CDH11, ICAM1 and CLDN3) were overexpressed in tumors when compared to normal esophagus, normal gastric and non-dysplastic Barrett's, and localized to the surface of tumor cells." (PMID 27363029, 2016).